E2F3 (E2F transcription factor 3)
Diseases named in the same sentence as E2F3 in open-access papers (continued):
Sharing a sentence is not in itself a finding about the gene and the disease.
pancreatic cancer (continued). "The high expression of E2F3 in pancreatic cancer samples was determined from the GEPIA website." (PMID 33854603, 2021). "Collectively, these findings suggest that targeting miR-573/E2F3 signaling may be a potential strategy in the treatment of pancreatic cancer." (PMID 33854603, 2021). "For example, the downregulation of miR-210 in pancreatic cancer could promote cell proliferation and tumor progression by regulating the expression of E2F3." (PMID 34036176, 2021). "Pancreatic cancer cells were transfected using an miR-573 mimic or siRNA E2F3." (PMID 33854603, 2021). "Besides, we analyzed the correlation between E2F3 expression and tumor stage in patients with pancreatic cancer on the GEPIA website." (PMID 33854603, 2021). "In this study, we aimed to determine whether miR-573 could suppress pancreatic cancer cell proliferation, migration, and invasion by targeting E2F3." (PMID 33854603, 2021). "Furthermore, E2F3 was up-regulated in pancreatic cancer tissues and cell lines and E2F3 down-regulation inhibited the proliferation, migration, and invasion of pancreatic cancer cells." (PMID 33854603, 2021). "Contrary to miR-194-5p, E2F3 overexpression promoted cell cycle progression and EdU incorporation, and hindered attenuation of pATM and γH2A.X and reduction of DNA damage in irradiated pancreatic cancer cells." (PMID 32228703, 2020). "The expression of HMGA2 was positively correlated with E2F3 in pancreatic cancer." (PMID 32228703, 2020). "MiR-217 inhibits pancreatic cancer cell proliferation via targeting E2F3." (PMID 31737898, 2019). "The miR-573/E2F3 axis might serve as a novel biomarker to predict the progression and prognosis of pancreatic cancer, as well as a potent therapeutic target in the treatment of pancreatic cancer." (PMID 33854603, 2021). "Nevertheless, the biological relevance of miR‐573/E2F3 in pancreatic cancer remains unclear." (PMID 33854603, 2021). "Its impact on downstream target genes like E2F3, EFNA3, GIT2, MNT, ZNF462, HOXA9, and EGR3 underscores its significance in shaping the aggressive phenotype of pancreatic cancer cells." (PMID 38132457, 2023). "By analyzing 171 normal pancreatic tissues and 179 pancreatic cancer tissues on the GEPIA website, we found the mRNA expression levels of E2F3 were significantly higher in patients with pancreatic cancer than in the normal control patients." (PMID 33854603, 2021). "The primary increased functions of E2F3 in KEGG analyses were related to apoptosis, B cell receptor signaling pathway, JAK-STAT signaling pathway, MAPK signaling pathway, pancreatic cancer, T cell receptor signaling pathway, and TGF beta signaling pathway." (PMID 33854603, 2021). "Down-regulation of Cdk4, Cdk6, E2F3, and E2F1 expression increases G0/G1 cell cycle arrest in pancreatic cancer cells." (PMID 27613829, 2016). "Cdk4, Cdk6, E2F3, and E2F1 play key roles in the regulation of cell cycle progression in pancreatic cancer." (PMID 27613829, 2016). "We further detected the expression of E2F3 in pancreatic cancer tissues and corresponding adjacent normal tissues using qRT-PCR." (PMID 33854603, 2021). "Surprisingly, we found that four crucial microRNAs (miR-34a-5p, miR-195-5p, miR-30c-5p, and miR-130b-3p) regulated the expression of many mRNAs (Cdk4, Cdk6, VEGF, IKKα, MEK1, E2F3, Rac1, E2F1, ERK1, and CDC42) and their proteins, and thus were crucial to the anti-pancreatic cancer effects of DHA." (PMID 27613829, 2016). "To determine protein levels of the mRNAs modulated by DHA via microRNAs, we next examined Cdk4, Cdk6, VEGF, IKKα, MEK1, E2F3, Rac1, E2F1, and CDC42 protein levels, which affect growth, inhibit angiogenesis, and promote apoptosis in DHA-treated and vehicle-treated pancreatic cancer cells." (PMID 27613829, 2016). "Besides, Pearson's correlation analyses showed a significant negative correlation between the expression of E2F3 and miR-573 in pancreatic cancer tissues (r=-0.5283, p=0.0004)." (PMID 33854603, 2021).
melanoma (25 papers, 2013 to 2025). A malignant, usually aggressive tumor composed of atypical, neoplastic melanocytes. "Other studies reported that a decrease of several non-coding RNAs resulted in an increase of E2F3 in melanoma." (PMID 40299364, 2025). "We then checked their expression and prognostic correlations in melanoma samples using TCGA SKCM datasets and GTEx normal samples and found that only E2F3 was both upregulated in melanoma and associated with a poor prognosis." (PMID 40299364, 2025). "Another lncRNA, nuclear paraspeckle assembly transcript 1 (NEAT1), promotes melanoma growth and invasion via the miR-495-3p–E2F3 axis, inhibiting miR-495-3p and inducing E2F3, which is known to promote proliferation." (PMID 41463281, 2025). "We found that CENPF, E2F3, KIRREL, METRN were both upregulated and associated with worse OS in melanoma patients." (PMID 40299364, 2025). "They found that H19 acts as a sponge for miR-106a-5p, leading to the upregulation of E2F3 transcription factor expression in melanoma cells." (PMID 33652661, 2021). "NEAT1 was also proved to facilitate the melanoma cell proliferation, migration, and invasion via regulating miR-495-3p and E2F3." (PMID 33392203, 2020). "The lncRNA NEAT1 has been reported to facilitate melanoma cell proliferation, migration, and invasion via regulating miR-495-3p and E2F3." (PMID 33392203, 2020). "In melanoma cell lines, ectopic expression of miR-377 was observed to inhibit proliferation and reduce colony formation by decreasing both E2F3 and MAP3K7 protein levels." (PMID 28947999, 2017). "Scholars hold the view that miR-377 regulates the NF-κB signaling pathway through MAP3K7 by directly targeting E2F3 in malignant melanoma." (PMID 28947999, 2017). "In malignant melanoma, miR-203 was reported to induce senescence by cell cycle arrest through targeting E2F3." (PMID 28947999, 2017). "Initial observations suggested a link between miR-377 and E2F3, and ectopic miR-377 expression decreased migratory capacity in melanoma cells by targeting E2F3." (PMID 28947999, 2017). "It was recently shown that targeting of E2F3 in melanoma cells by miR-203 inhibited cell growth and induced cell cycle arrest and senescence." (PMID 25889255, 2015). "We found that E2F3, which is over-expressed in melanoma, is a direct target of miR-377 and its activity is regulated by miR-377." (PMID 25889255, 2015). "For example, it was recently shown that targeting E2F3 by miR-203 in melanoma cells inhibited cell growth and induced cell cycle arrest and senescence." (PMID 25889255, 2015). "Ectopic stable over-expression of miR-377 in melanoma cell lines decreased both E2F3 and MAP3K7 protein levels and led to inhibition of proliferation, migration and colony formation." (PMID 25889255, 2015). "E2F3, a potent transcriptional inducer of cell-cycle progression, was found to be elevated in melanoma cell lines, but decreased following ectopic expression of miR-377." (PMID 25889255, 2015). "When miR-377 was over-expressed in melanoma cells, the level of E2F3 mRNA was almost unchanged (left)." (PMID 25889255, 2015). "Its upregulation drives tumor progression through cell cycle dysregulation and immune evasion, while targeting the E2F3-CENPF axis may offer a novel strategy for melanoma treatment." (PMID 40299364, 2025). "Among them, miR-495-3p was reported to target E2F transcription factor 3 (E2F3), which could induce melanoma cell proliferation, migration, and invasion by promoting the transformation of G1 to S." (PMID 36612077, 2022). "Overexpressed KLF3 and E2F3 increased melanoma proliferation, migration and invasion." (PMID 34638331, 2021). "In malignant melanoma, expression of the lncRNA H19 was shown to be increased in melanoma tissue and might function as a sponge of miR-106a-5p to upregulate E2F3 expression and consequently promote the glucose metabolism and growth of melanoma cells." (PMID 32765426, 2020).
melanoma (continued). "The long non-coding RNA-H19 could act as a ceRNA, bind to miR-106a-5p and upregulates E2F3, thereby promoting glucose metabolism and cell growth in malignant melanoma cells." (PMID 31427569, 2019). "When we crossed this list with the list of down regulated mRNAs in miR-377-expressing melanoma cells, we found 4 putative transcripts with miR-377-binding sites: E2F3 (a putative target of miR-377 in 6 out of 10 software), MAP3K7 (in 4 out of 10), KRAS (in 5 out of 10) and CDK6 (in 5 out of 10)." (PMID 25889255, 2015). "E2F3 mRNA and protein levels were higher in melanoma cell lines compared to NHEM." (PMID 25889255, 2015). "It is tempting to speculate that silencing of miR-377 in melanoma unleashes both the E2F3 and NF-kB signaling pathways, promoting the tumorigenic and metastatic potential of the cells." (PMID 25889255, 2015). "We show here that the expression of miR-377 is completely silenced in melanoma cell lines and samples, and that it directly targets both the transcription factor E2F3 and MAP3K7, a tyrosine kinase along the MAPK pathway, known to be important in the activation of the NF-kB signaling pathway." (PMID 25889255, 2015). "miR-203 induces senescence by targeting the E2F3 protein in human melanoma cells." (PMID 24282530, 2013). "Moreover, E2F3 was reported to promote melanoma cell growth through copy number variation." (PMID 40299364, 2025). "Next, plasma cfRNA samples from melanoma patients (N = 18) versus control plasma of healthy donors (N = 18) were used to determine gene expression levels of six gene candidates (KPNA2, DTL, BACE2, DTYMK, E2F3 and SLC25A13) that showed excellent diagnostic accuracy (AUC >90.0%) in tissue." (PMID 36320118, 2022). "LncRNA-H19 via miR-106a-5p/E2F3 axis could promote glucose metabolism in malignant melanoma." (PMID 33123468, 2020). "Another work showed that miR-377 was a key regulator of E2F3 and MAP3K7/NF-κB pathways in melanoma progression, rendering it a potential new therapeutic target in melanoma." (PMID 28947999, 2017). "mRNA arrays of melanoma cells over-expressing miR-377 pointed to several down-regulated mRNAs that have putative binding sites for miR-377 in their 3′UTR, of which both E2F3 and MAP3K7 were found to be direct targets of miR-377." (PMID 25889255, 2015). "In conclusion, we identified the E2F3–CENPF axis in melanoma, which contributes to melanoma’s high proliferative ability, and demonstrated that knocking down CENPF could inhibit melanoma cell proliferation and induce cell apoptosis." (PMID 40299364, 2025). "Receiver operating characteristic (ROC) curves showed an area under the curve (AUC) >90.0% for KPNA2, DTL, BACE2, DTYMK, E2F3 and SLC25A13, >80.0% for CCNA2, FOXM1, KIF4A, SLC45A2, COPS8, SLC45A13 and 70.0% for CDC25A and LINC00520; all significantly discriminating melanoma from benign nevi." (PMID 36320118, 2022). "Moreover, H19 functions as a sponge for miR-106a-5p, a tumor suppressor miRNA that targets E2F3, and miR-18b that targets IGF1 H19-mediated upregulation of E2F3 promotes glucose metabolism and growth of melanoma cells." (PMID 34638331, 2021).
glioma (22 papers, 2014 to 2026). A benign or malignant brain and spinal cord tumor that arises from glial cells (astrocytes, oligodendrocytes, ependymal cells). "All E2Fs (except for E2F3 and E2F5) are highly expressed in high-grade gliomas (HGG) and linked to grade progression, indicating an adverse outcome." (PMID 35409080, 2022). "Among the eight E2F family members, up-regulated E2F1 expression gene reportedly induced apoptosis in glioma cell lines, while E2F3 knockdown inhibited proliferation and migration in glioma." (PMID 34617871, 2021). "Conversely, elimination of E2F3 attenuates proliferation, migration, and invasion and accelerates apoptosis of glioma cells." (PMID 32348429, 2020). "E2F3 overexpression is a cancer suppressor event in many types of tumors, including brain and CNS cancers." (PMID 33381564, 2020). "Second, through a series of assays, we concluded that SNHG5 acts as a sponge for miR-205, which inhibits tumour growth in glioma by targeting E2F transcription factor 3 (E2F3)." (PMID 31292168, 2019). "qRT-PCR, Western blotting and immunofluorescence were performed to detect E2F3 expression in glioma cell lines." (PMID 31292168, 2019). "Taken together, we found that SNHG5 modulates glioma progression by sponging miR-205 to up-regulate E2F3 expression." (PMID 31292168, 2019). "Next, through a series of assays, we concluded that SNHG5 functions as a sponge for miR-205, which inhibits tumour growth in glioma by targeting E2F transcription factor 3 (E2F3)." (PMID 31292168, 2019). "SNHG5 promotes the glucose uptake, migration and invasion of glioma cells by sponging miR-205 and up-regulating E2F3 expression." (PMID 31292168, 2019). "Another study showed that miR-203 expression was also lower in highly invasive glioma cells or tissues and the inverse expression patterns between miR-203 and E2F3 in invasive glioma tissues were verified." (PMID 28947999, 2017). "Another report showed that miR-203 was positively correlated with the sensitivity of glioma cells to chemotherapy and re-expression of miR-203 increased glioma cells to temozolomide by targeting E2F3." (PMID 28947999, 2017). "Accordingly, miR128-1 overexpression resulted in reduced expression of both BMI1 and E2F3 in glioma cells and GSCs." (PMID 27705931, 2016). "LINC00467 accelerated the progression of gliomas by regulating the miR-200a/E2F3 axis." (PMID 35719391, 2022). "Moreover, LINC00467 was shown to promote the viability, migration, and invasion of glioma cells, and its expression level was negatively correlated with that of miRNA-200a, but positively correlated with E2F3 expression." (PMID 35719391, 2022). "For example, E2f3 expression is posttranscriptionally regulated by miR-128 in glioma." (PMID 34173119, 2021). "In summary, these results confirm that miR-205 plays a role through E2F3 in glioma cells." (PMID 31292168, 2019). "Taken together, our results show that the SNHG5/miR-205/E2F3 axis is involved in glioma progression and may provide a new therapeutic target for the diagnosis and therapy of glioma." (PMID 31292168, 2019). "E2F3 belongs to the E2F transcription factor family, which can affect glioma progression." (PMID 31292168, 2019). "We intensively investigated whether SNHG5 drives the glucose uptake, migration and invasion of glioma cell lines via E2F3 in a miR-205-dependent manner." (PMID 31292168, 2019). "Our present study showed that SNHG5 promotes the expression of E2F3 in glioma." (PMID 31292168, 2019).
glioma (continued). "Our study not only furthers the understanding of the regulatory mechanism of the SNHG5/miR-205/E2F3 axis in glioma but also may lead to a new potential strategy for glioma therapy." (PMID 31292168, 2019). "The findings suggested that miR-128-1 could impede the growth of glioblastoma and GSCs via targeting BMI1 and E2F3, so miR-128-1 and DNA demethylating agents were promising for anti-glioma therapy at least in part by eliminating GSCs." (PMID 28947999, 2017). "Previous studies have shown that miR-128 targets E2F3 and inhibits cell proliferation in glioma." (PMID 28362317, 2017). "The glad news was put forward that miR-203 may function as a tumor suppressor in glioma progression, suggesting that targeting miR-203/E2F3 axis could be a rational therapeutic strategy for glioma." (PMID 28947999, 2017). "Whether HDACs regulate the expression of RAD18 through E2F3 in gliomas is still unknown." (PMID 35365623, 2022). "Interestingly, SNHG5 promoted the development of glioma by targeting E2F3." (PMID 33381564, 2020). "In glioma, SNHG5 sponges miR-205 to upregulate E2F3, thereby increasing glucose uptake and lactate production." (PMID 41550840, 2026). "By acting as a sponge for miR-205, which targets E2F transcription factor 3 (E2F3), SNHG5 enhances glioma growth." (PMID 33652661, 2021). "E2F5, E2F7, and E2F8 were significantly upregulated in brain and CNS cancers relative to normal brain samples, while E2F1 and E2F3 were more highly expressed in normal brain samples in the ONCOMINE dataset." (PMID 34617871, 2021). "In glioma, HELLS regulates the proliferation of stem cell-like glioblastoma stem cells by interacting with key oncogenic TFs E2F3 and MYC; targeted the inhibition of HELLS and prolonged survival in mice and improved the prognosis of patients with increased HELLS expression." (PMID 35774795, 2022). "A recent study suggested that miR-128-1 was downregulated in GBM and glioma stem-like cells (GSCs) and miR-128-1 could inhibit the growth of glioblastoma multiforme and glioma stem-like cells via targeting BMI1 and E2F3." (PMID 28947999, 2017). "Additionally, we verified that SNHG5 enhances the expression of E2F3 by competitively binding to miR-205 and that the effect of si-SNHG5 on glioma cells could be impaired by the miR-205 inhibitor." (PMID 31292168, 2019).